HGF (hepatocyte growth factor)
Diseases named in the same sentence as HGF in open-access papers (continued):
Sharing a sentence is not in itself a finding about the gene and the disease.
metastatic cancer (12 papers, 2012 to 2025). A carcinoma which has spread from the original site of growth to another anatomic site. "Since increased expression of MET and phosphorylation in cancer cells was confirmed, the data suggested that the metastatic cancer cells mainly bind with HGF, which is released into the pericancerous liver microenvironment in a paracrine manner." (PMID 40076928, 2025). "It was shown that the concentration of HGF in the serum was significantly higher in patients with more advanced stages of metastatic cancer than in patients with less advanced cancer." (PMID 32607415, 2020). "Treatment with hepatocyte growth factor (HGF) activated c-Met in two metastatic cancer cell lines BSp73ASML and HT29 and this was inhibited by neutralizing antibodies to CD44v6." (PMID 29747682, 2018). "Our results proved that HGF/MET axis plays a crucial role in directing cell-autonomous functions regulating cancer cell dissemination, supporting a possible use of MET inhibitors in metastatic cancers." (PMID 37345079, 2023). "Even with the negative results from the multiple clinical trials, c-Met/HGF remains an important therapeutic target for metastatic cancers, including bone metastasis." (PMID 30658428, 2019). "MAF-specific knockout of HGF and HAS2 decreases metastatic tumor growth and strongly extends the survival of mice, suggesting that HGF and HAS2 may be therapeutic targets for desmoplastic metastatic cancers." (PMID 34112258, 2021). "For instance, HGF and TGFβ are major regulators of EMT, and these also provide strong stimuli of GBM invasion and, upregulation of MET and CD44 activities, as well as an activated NFκB signaling pathway, was reported in both mesenchymal GBM and metastatic cancer." (PMID 31009513, 2019).
neuroblastoma (12 papers, 2008 to 2025). Neuroblastoma (NB) is the most common solid, extracranial childhood tumor. "Vascular endothelial growth factor (VEGF) and hepatocyte growth factor (HGF)/c-MET signalling are implicated in neuroblastoma progression." (PMID 40359728, 2025). "Several angiogenic signalling pathways have been implicated in neuroblastoma progression, including vascular endothelial growth factor (VEGF), the most potent angiogenic growth factor, and the hepatocyte growth factor (HGF) receptor MET." (PMID 40359728, 2025). "Although they did not observe any effects on in vitro proliferation, the authors reported a very clear role for HGF/MET signaling in migration/invasion of neuroblastoma cells, both in vitro and in vivo." (PMID 34716856, 2022). "The same group also showed that NTRK2 activation preceded and mediated HGF/MET upregulation in neuroblastoma cell lines." (PMID 34716856, 2022). "Regarding neuroblastoma, initial studies demonstrated a role for HGF/MET signaling in the migration and/or differentiation of neural crest cell-derived structures." (PMID 34716856, 2022). "The neuroblastoma SK-N-SH cells with HGF overexpression which activates MET signalling are sensitive to MET inhibitors." (PMID 31137515, 2019). "This study was designed to investigate the protective effect of hUC-MSCs infected by an adenovirus carrying the HGF gene on the PD cell model induced by MPP+ on human bone marrow neuroblastoma cells." (PMID 25276829, 2014). "The important downstream effector of HGF/c-Met signaling that promotes neuroblastoma progression is STAT3, one of the well-recognized signal transduction pathways involved in angiogenesis and other steps in cancers." (PMID 21876694, 2012). "HGF and c-Met are upregulated in many human cancers including neuroblastoma and highly responsible for neuroblastoma invasion in vitro and in vivo." (PMID 21876694, 2012). "Another inhibitor PHA665752 has been reported to suppress c-Met activity and block HGF-induced cell migration and proliferation of c-Met-positive neuroblastoma cells." (PMID 21876694, 2012). "This study investigated c-Met and HGF expression in two neuroblastoma (NBL) cell lines and tumor tissue from patients with NBL, as well as the effects of PHA665752 on growth and motility of NBL cell lines." (PMID 19939254, 2009). "Expression of c-Met and/or HGF has been detected in cell lines established from pediatric tumors including rhabdomyosarcoma, osteogenic sarcoma, and neuroblastoma." (PMID 19939254, 2009). "Overexpression of TRKB also mediates cmet activation via upregulation of HGF and cooperation between TRKB and cmet has been implicated in the invasive capability of neuroblastoma cell lines." (PMID 18382428, 2008). "However, the development of novel small molecule inhibitors targeting c-MET activity has prompted to a re-evaluation of HGF/MET signaling in neuroblastoma and other cancer paradigms." (PMID 34716856, 2022). "Combinations of all-trans retinoic acid, EZH2 inhibitors, and antibodies targeting the hepatocyte growth factor (HGF) with agents targeting the ganglioside GD2 (an already established immunotherapy target in neuroblastoma) have shown promising results in preclinical studies." (PMID 35626150, 2022). "Thus, targeting HGF/c-Met signaling pathways could be a beneficial approach for controlling angiogenesis in neuroblastoma." (PMID 21876694, 2012). "Furthermore, they also found that sublethal irradiation led to upregulation of HGF and MET in neuroblastoma cell lines, resulting in enhanced migratory behavior." (PMID 34716856, 2022). "The ganglioside GD2, well-established as an immunotherapy target in neuroblastoma, may also have promise in EwS, when combined with other agents such as all-trans retinoic acid, EZH2 inhibitor or antibody targeting HGF." (PMID 33919988, 2021).
neuroblastoma (continued). "The HGF overexpression in SK-N-SH cells would activate MET signalling and be responsible for the cancer cell growth, which is accordant with the clinical status of neuroblastoma cancer patients." (PMID 31137515, 2019).
oral cancer (12 papers, 2012 to 2025). "Based on our clinical samples and in vivo evidence, our research supports the view that HGF expression is associated with tumor size and the stage of oral cancer, and HGF overexpression can slow tongue tumor induction by 4NQO." (PMID 34970484, 2021). "These trends of nanophotosensitizers are related to the generation of ROS and PDT efficacy, i.e., the COSthPBAP nanophotosensitizers showed superior ROS generation and PDT efficacy against oral cancer cells with low dark toxicity against normal HGF-1 cells." (PMID 36295132, 2022). "In oral cancer models, HGF-Tg mice had a smaller tumor number and tumor volume and a higher survival rate than Wt mice." (PMID 34970484, 2021). "The authors also observed that myofibroblasts secreted greater quantities of HGF when compared to primary fibroblasts, and that HGF promoted oral cancer cell invasion into a Matrigel matrix." (PMID 23503917, 2013). "However, the exact expressions of MET/HGF pathway correspond to MET polymorphisms and oral cancer progression and prognosis require future well-designed study to elucidate it." (PMID 39991569, 2025). "As receptors for SRPX2, urokinase plasminogen activator receptor (uPAR) and hepatocyte growth factor (HGF) are known, and it was found that SRPX2 was secreted into the culture supernatant by treating oral cancer cell lines with recombinant proteins of uPAR and HGF." (PMID 35330413, 2022). "Moreover, HGF overexpression in normal tissues can inhibit cell proliferation and accelerate apoptosis in the progression of oral cancer potentially by downregulating MAPK and PI3K-AKT according to KEGG enrichment analysis." (PMID 34970484, 2021). "In addition, compared with normal epithelium, HGF and its receptor c-Met were positively expressed in dysplastic and tumor tissues in an oral cancer model of Wt mice." (PMID 34970484, 2021). "Intriguingly, we discovered that activation of the HGF/c-Met signaling pathway can inhibit the occurrence of oral cancer, although aberrant HGF and c-Met expression in tumor tissues is considered to be a promoting factor for the development of various types of cancer." (PMID 34970484, 2021). "In a 24 h MTS assay, the low dose EANA (5 μg/mL) and low dose UVC (12 J/m2) individually show 80% and combinedly 57% cell proliferation in oral cancer Ca9-22 cells; but no cytotoxicity to normal oral HGF-1 cells." (PMID 32948007, 2020). "Together, these data indicate that BM cells are recruited into the oral cancer TME through the action of the stroma factor CCL2 and not by SDF-1 and HGF." (PMID 34874922, 2022).
sarcoma (12 papers, 2008 to 2023). A usually aggressive malignant neoplasm of the soft tissue or bone. "The FNCLCC histological grading of sarcomas correlated significantly with HGF expression (score 0–2), since higher histologic grade was associated with stronger HGF expression (p<0.001, Chi Square)." (PMID 25844809, 2015). "To translate our findings from cell line models to patients, we analyzed circMET in formalin-fixed paraffin-embedded (FFPE) tumors, including both HGF-driven murine sarcomas and human lung and colon adenocarcinomas (ADK)." (PMID 37170152, 2023). "Here we investigate the relevance of the satellite cell (SC) niche in sarcoma development by using Hepatocyte Growth Factor (HGF) to perturb the niche microenvironment." (PMID 26987019, 2016). "Although others have linked injury with sarcoma also through activation of Met signaling, we here describe a unique model aimed at investigating the effect of HGF-mediated SC niche perturbation in sarcoma development and maintenance." (PMID 26987019, 2016). "Altogether, our data show that perturbation of the SC niche with HGF can promote distinct sarcoma subtypes in a Pax7 lineage-dependent manner, thus offering a possible explanation of why ERMS and UPS are part of a tumor continuum." (PMID 26987019, 2016). "6/9 tumors (67%) were simultaneously positive for MET and HGF, i.e., 3/5 undifferentiated pleomorphic sarcomas, and 3/4 angiosarcomas showed 2+ staining for both proteins (p<0.001, Chi Square and Fisher’s exact)." (PMID 25844809, 2015). "Our goal was to determine the prevalence of the three major mechanisms of MET activation, i.e., MET gene amplification, and MET as well as HGF protein overexpression in clinically relevant sarcoma entities." (PMID 25844809, 2015). "Combined overexpression of HGF and c-MET have been observed in numerous sarcomas, and HGF can activate c-MET in an autocrine manner in these tumors." (PMID 25098767, 2014). "Cmet has previously been detected in 52–87% of STS and, an important proto-oncogene itself, also enables sarcoma cells to become hyper-responsive to HGF, a ubiquitously expressed effector of cell proliferation, motility and invasiveness." (PMID 18382428, 2008). "Only few preclinical studies, however, dealt with inhibition of HGF/MET axis in sarcomas, but they could show antitumoral effects on growth, viability, invasion and metastasis in vitro and in vivo." (PMID 25844809, 2015). "Therefore, we provide evidence that these sarcoma entities are candidates for upcoming clinical trials with compounds inhibiting the HGF/MET axis." (PMID 25844809, 2015). "To examine whether pazopanib has the similar effects on other sarcoma cell line, we used Asra-Eps, which was our established epithelioid sarcoma cell line driven by HGF/c-MET signaling." (PMID 24946937, 2014). "For example, SST0001, a modified heparin, significantly reduces in vivo heparanase activity and controls levels of growth factors including HGF and VEGF, thereby preventing angiogenesis in human pediatric sarcoma models." (PMID 35118073, 2021). "In summary, we investigated a comprehensive series of more than 400 adult-type sarcomas for MET and HGF overexpression as well as for MET gene amplification." (PMID 25844809, 2015). "The HGF/c-MET signaling pathway is critical in cell proliferation, motility, and invasion of several human sarcomas, but little is known about its biological functions in EpS." (PMID 25098767, 2014). "However, when HGF was turned on in similar mice that also lacked normal muscle stem cells, the resulting sarcomas were predominantly undifferentiated pleomorphic sarcomas." (PMID 26987019, 2016). "Among all clinical trials listed at clinicaltrials.gov for MET and HGF inhibitors four studies are open explicitly for patients with sarcomas and there are multiple studies open to patients with not further specified solid tumors, which could include also soft tissue sarcomas (June 2014)." (PMID 25844809, 2015).
viral infection (12 papers, 2009 to 2026). "We further characterized the phenotype of HGF-UCMSCs using flow cytometry 48 hours after viral infection." (PMID 27057357, 2016). "In order to fabricate a stable model of CTE to support further viral infection studies we first sought to characterize appropriate primary fibroblasts or immortalized fibroblastic cell lines of various origins, namely HGF and hTERT-HGF (oral mucosa), FSF (foreskin) and MRC-5 cells (embryonic lung)." (PMID 35935486, 2022). "Some anti-fibrotic factors, namely SMAD6, SMAD7, STAT1, and HGF, were also induced by the virus infection, although to a lesser extent compared to pro-fibrotic upregulation, perhaps as a counterbalance of the potent pro-fibrotic expression induced in vitro by virus infection." (PMID 31878218, 2019). "To examine the functional relevance of LECT2 in viral infection, we evaluated LECT2, MET and HGF mRNA expression in the liver of patients with chronic hepatitis C (CHC)." (PMID 35676290, 2022). "Worthy of remark is that HGF and eotaxin were found to be elevated in patients with severe influenza A (H1N1) virus and other viral infections and in patients with inflammatory lung injury.." (PMID 36238287, 2022). "The addition of HGF before or after viral infection did not affected rLCMV/LASVGP relative infectivity, whereas its presence during viral entry increased rLCMV/LASVGP entry in approximately 40%." (PMID 32781509, 2020). "In addition, it has been demonstrated that inflammatory cytokines, such as oncostatin M (OSM), hepatocyte growth factor (HGF), interferon-γ (IFN-γ), and toll-like receptors 7 and 8 (TLR7/8), when stimulated by viral infections, can trigger KSHV reactivation." (PMID 25594835, 2015). "HGF, FGF-basic and VEGF were produced at high levels and may reflect a physiological response to tissue destruction resulting for the viral infection." (PMID 19156204, 2009). "Furthermore, the lack report of MIF, SCF, HGF, MCP-1 and SCGF-β elevations in lethal virus infections may be due to the lack of laboratory examinations." (PMID 26028236, 2015).
acute GVHD (11 papers, 2006 to 2022). "Previous studies demonstrated that cDNA-encoding HGF administration could inhibit acute graft-versus-host disease (GVHD) after treatment via hematopoietic stem cell transplantation." (PMID 35889092, 2022). "In murine allogeneic bone marrow transplantation, HGF ameliorated acute graft-versus-host disease (aGVHD) through the reduction of IL12 serum levels and suppression of target organ IFNγ and TNFa mRNA26." (PMID 27917866, 2016). "The four markers, CXCL8, IL2R-α, TNFR1 and HGF, identified above showed increased levels in acute GVHD, and increased levels of these markers have also been identified in other clinical studies." (PMID 23430540, 2013). "We described that high pretransplant levels of HGF are associated with an increased risk of GVHD, whereas the posttransplant development of acute GVHD is associated with an increased risk of acute GVHD (see the detailed discussion below)." (PMID 23430540, 2013). "HGF also exerted a potent protective effect on thymus, which in turn inhibited the development of autoreactive T cells in the thymus damaged by acute GVHD." (PMID 16859527, 2006). "We previously reported that repeated transfection of the human HGF gene into skeletal muscle of allogeneic HSCT recipients reduced the tissue damage and subsequent inflammatory responses caused by acute GVHD." (PMID 17049072, 2006). "Thus, HGF treatment may be beneficial for both Th1-mediated acute GVHD and Th2-mediated autoimmune chronic GVHD." (PMID 16859527, 2006). "Notably, the presence of acute GVHD in our cohort of patients seem not to affect the assessment of systemic inflammatory parameters, except for the levels of HGF and TGF-β." (PMID 34956203, 2021). "Finally, several strategies for inhibition of HGF or HGF-induced intracellular signaling are currently being developed, but to the best of our knowledge, this strategy has not been investigated in clinical trials for patients with acute GVHD." (PMID 23430540, 2013). "While spleen cells from both untreated and HGF-treated chronic GVHD mice showed no specific CTL activity toward host-type EL-4 cells, spleen cells from acute GVHD mice showed CTL activity against host-type P815 cells (data not shown)." (PMID 16859527, 2006).